PLS1 (plastin 1)
Description:
Actin-bundling protein. In the inner ear, it is required for stereocilia formation. Mediates liquid packing of actin filaments that is necessary for stereocilia to grow to their proper dimensions.
Synonyms: DFNA76
Tractability: Antibody: its Gene Ontology location is reachable by antibodies, with high confidence; the Human Protein Atlas places it where antibodies can reach. PROTAC: ubiquitination databases record sites on it; its protein half-life has been measured.
Gene: Protein-coding gene on chromosome 3 (142,595,644 to 142,713,869, forward strand). Ensembl gene ENSG00000120756.
Subcellular location: Cytoplasm; Cell projection, stereocilium
Subcellular location (Human Protein Atlas): Plasma membrane
Pathways (Reactome):
Sensory Perception: Sensory processing of sound by inner hair cells of the cochlea; Sensory processing of sound by outer hair cells of the cochlea
Gene Ontology:
Molecular function: actin filament binding; structural constituent of cytoskeleton; calcium ion binding
Biological process: auditory receptor cell stereocilium organization; positive regulation of protein localization to plasma membrane; vestibular receptor cell stereocilium organization; actin filament bundle assembly; intestinal D-glucose absorption; positive regulation of multicellular organism growth; regulation of microvillus length
Cellular component: extracellular exosome; actin filament; actin filament bundle; brush border; cytoplasm; stereocilium; terminal web
Genetic constraint (gnomAD): Loss-of-function variants: 9 observed, 22.5 expected, observed/expected ratio (o/e) 0.4, 90% interval 0.24 to 0.7. The upper end of that interval is the gene's LOEUF score, 0.7, which puts it in group 2 of 6, group 1 being the genes least tolerant of losing a copy. Missense variants: 167 observed, 223.73 expected, observed/expected ratio (o/e) 0.75, 90% interval 0.66 to 0.85. Synonymous variants: 68 observed, 87.3 expected, observed/expected ratio (o/e) 0.78, 90% interval 0.64 to 0.95.
Gene-disease validity (ClinGen):
ClinGen rates the evidence that PLS1 causes each of these diseases.
autosomal dominant nonsyndromic hearing loss (autosomal dominant): Moderate. Autosomal dominant form of nonsyndromic deafness.
Homologues: Orthologues: chimpanzee PLS1 (100% identical), macaque PLS1 (99% identical), rabbit PLS1 (96% identical), guinea pig PLS1 (96% identical), mouse Pls1 (94% identical), pig PLS1 (94% identical), rat Pls1 (94% identical), dog PLS1 (94% identical), tropical clawed frog pls1 (75% identical), zebrafish pls1 (73% identical), Drosophila melanogaster Fim (51% identical), Caenorhabditis elegans plst-1 (30% identical), and 1 more. Paralogues in human: PLS3 (75% identical), LCP1 (73% identical).
Diseases named in the same sentence as PLS1 in open-access papers:
PLS1 is named in the same sentence as 25 diseases in open-access papers, as found by Europe PMC text mining. Sharing a sentence is not in itself a finding about the gene and the disease. The quoted sentences say what the papers report.
colorectal cancer (3 papers, 2021 to 2023). A primary or metastatic malignant neoplasm that affects the colon or rectum. "PLS1 has been reported to promote metastasis of colorectal cancer through the IQGAP1/Rac1/ERK pathway." (PMID 36895481, 2023). "PLS1 drives metastasis of colorectal cancer through the IQGAP1/Rac1/ERK pathway and promotes osteoblast differentiation by regulating intracellular Ca2+." (PMID 34290731, 2021).
hearing loss (3 papers, 2015 to 2021). "Some types of actin-mediated hearing impairment are influenced by mutations in the human PLS1 gene." (PMID 32454462, 2020). "Interestingly, the human PLS1 gene maps to 3q23, and this chromosomal region has been associated by linkage analysis to progressive forms of hearing impairment in the elderly." (PMID 25124451, 2015). "Further studies should be conducted to investigate whether mutations or reduced expression of the PLS1 gene are indeed linked to age-related hearing loss in humans." (PMID 25124451, 2015). "Hence, mutations in the human PLS1 gene may be associated with relatively mild and progressive forms of hearing loss." (PMID 25124451, 2015). "Hence, mutations in the human PLS1 gene could be associated with mild and progressive forms of hearing loss." (PMID 25124451, 2015). "The DFNA18 locus, a dominant progressive form of hearing loss, lies in the same region, but currently available mapping and linkage analysis data would suggest that it does not encompass the PLS1 gene." (PMID 25124451, 2015).
periodontitis (2 papers, 2022 to 2023). An acute or chronic inflammatory process that affects the tissues that surround and support the teeth. "Plastin-1 was an example of a protein exclusively identified in US samples from periodontitis groups (OP and NP)." (PMID 37408223, 2023). "Further investigations must pay attention to the role and the mechanism of Plastin-1 in periodontitis individuals." (PMID 36355174, 2022). "In our earlier study, we proposed that the existence of Plastin-1 in pregnant women with periodontitis may represent a compensation mechanism for the high levels of inflammation and bone loss, functioning to maintain bone homeostasis." (PMID 37408223, 2023). "As we mentioned in our recent study, to the best of our knowledge, there has never been any proof linking Plastin-1 with periodontitis." (PMID 37408223, 2023).
Alzheimer disease (1 paper, 2023). A progressive, neurodegenerative disease characterized by loss of function and death of nerve cells in several areas of the brain leading to loss of cognitive function such as memory and language. "“Dopaminergic synapse,” “Alzheimer’s disease,” and “pathways of neurodegeneration-multiple diseases” terms were enriched using merged PLS1 − genes, and “pathways in cancer” and “cell adhesion metabolism” terms were enriched with the highest significance using merged PLS1 + genes." (PMID 37400838, 2023).
cortical atrophy (1 paper, 2025). "Our analysis revealed distinct sets of PLS1 genes positively or negatively associated with cortical atrophy for C9orf72-bvFTD, GRN-bvFTD, and MAPT-bvFTD, potentially reflecting molecular mechanisms underlying neuroanatomical changes." (PMID 39920674, 2025).
deafness (1 paper, 2025). An inherited or acquired condition characterized by the complete loss of the ability to hear from one or both ears. "Genes from the CAPZA family were involved with the regulation of the growth of actin filament and associated deafness (e.g., PLS1, LHFL5, OTOG, ESPN, and ESPNL)." (PMID 41465109, 2025).
endometrioid carcinomas (1 paper, 2024). "Eight common proteins were identified between normal endometrium with diploid endometrioid carcinomas and diploid with aneuploid endometrioid carcinomas, namely ACTB, ATP5B, ATP5E, INS, IVNS1ABP, LMNB, PLS1, and VIM." (PMID 39194522, 2024).
lymph node metastasis (1 paper, 2021). "The PLS1 was overexpressed in CRC patients and associated with lymph node metastasis and a poor prognosis." (PMID 34796198, 2021).
primary immunodeficiency (1 paper, 2024). "The PLS1+ gene set is mainly enriched in the inflammatory and immune biological processes, such as “leukocyte activation”, “immune response-activating signaling pathway”, and “primary immunodeficiency”." (PMID 38351174, 2024).
spinal muscular atrophy (1 paper, 2023). A motor neuron disease that affect the muscles, and characterized by muscle weakness and atrophy resulting from progressive degeneration and irreversible loss of the anterior horn cells in the spinal cord (i.e., lower motor neurons) and the brain stem nuclei. "Another study on spinal muscular atrophy (SMA) showed that PLS2 was able to perform the same role as PLS3 in motor axons, thereby substituting for PLS3, albeit less efficiently, while PLS1 showed no ability to rescue these defects even though PLS1 could also bind and bundle actin." (PMID 37484945, 2023).
infection (10 papers, 2008 to 2024). The state of being infected such as from the introduction of a foreign agent such as serum, vaccine, antigenic substance or organism. "NoxB and Pls1 were reported to be associated with the ER and specifically accumulate in the infection structures in V. dahliae, Magnaporthe oryzae and Botrytis cinerea." (PMID 37108938, 2023). "Transcription of CCA00416 and CCA00417, that encode orthologs of Pls1 and Pls2 respectively appeared only mildly reduced 24 hours after infection." (PMID 22292031, 2012). "Functional analysis by gene replacement showed that these proteins, as well as Pls1, are involved in the infection process of the plant pathogenic fungus M. grisea." (PMID 18241352, 2008). "Furthermore, during plant infection with the pathogenic fungus M. grisea or B. cinerea, the tetraspanin PLS1 is required for infection site formation." (PMID 31437164, 2019). "In phytopathogenic fungi, Pls1 is essential for infection and is required for appressorium-mediated penetration into host plant in three species (M. grisea, B. cinerea,C." (PMID 18241352, 2008). "In addition to virtual infection, PLS1 + genes of EOS1 were enriched in calcium signaling and MAPK signaling pathways, which are implicated in the onset of SCZ by regulating neuronal excitability and neural development." (PMID 38049797, 2023). "However, mitogen activator (PMK1, MPS1), ATPase (PDE1), Tetraspanins (PLS1), and fungal effector genes were reported as important genes for infection in rice blast fungus." (PMID 36213126, 2022). "M. oryzae mutants unable to infect wounded plant as Δbip1, were affected in genes essential for penetration peg formation like PLS1, NOX2, MPS1 or MST12, or crucial for establishing primary infection hyphae within infected plant cells." (PMID 38252628, 2024). "When plants are infected with the pathogenic fungus Magnaporthe grisea, the fungal tetraspanin Pls1 and an NADPH oxidase are localized at the infection sites or appressorium structure to generate a ROS accumulation response that is required to reestablish the appressorium polarity." (PMID 31437164, 2019).
cancer (4 papers, 2014 to 2023). A tumor composed of atypical neoplastic, often pleomorphic cells that invade other tissues. "As to the KEGG pathways, the PLS1 genes were significantly enriched in cAMP signaling and morphine addiction and cancer pathways." (PMID 36937723, 2023). "Interestingly, PLST belongs to the plastin protein family of three isoforms with relatively high homology between: I (plastin-1 expressed in the intestine and kidney), L (plastin-2 in leukocytes and cancer) and T (plastin-3 in solid tissues)." (PMID 25525413, 2014). "Three plastin isoforms are expressed in vertebrates: PLS1 (I-plastin) is expressed in absorptive intestinal and kidney cells, PLS2 (LCP, LCP1, or L-plastin) is predominantly found in hematopoietic and cancer cells, while PLS3 (T-plastin) is ubiquitously expressed in all solid tissues." (PMID 37484945, 2023).
tumor (2 papers, 2021 to 2025). "Up to now, there are few reports on the association between EIF5A2, HGD, HS6ST1, PLS1, PTHLH, and YEATS2 methylation modification and tumor." (PMID 34796198, 2021).
brain disorder (1 paper, 2022). A disease affecting the brain or part of the brain. "Finally, we investigated whether PLS1+ and PLS1− are enriched for pain-related and other brain disorder-related genes as identified in previous studies." (PMID 34561394, 2022).
PLS1 also shares sentences with these, for which no sentence is quoted: Hearing impairment (2 papers); age (1); cervical cancer (1); colitis (1); colon cancers (1); glioma (1); Listeria monocytogenes infection (1); melanoma (1); Obesity (1); osteoporosis (1); Parkinson disease (1).